IL1B (interleukin 1 beta)
Diseases named in the same sentence as IL1B in open-access papers (continued):
Sharing a sentence is not in itself a finding about the gene and the disease.
infection (continued). "To demonstrate whether reduced IL-1β secretion is directly associated with the absence of the bacterial secretion system assessed and not to decreased bacterial infectivity, we quantified the CFUs at 1 h post-infection and determined the invasion index relative to the parental (wt) strain." (PMID 22848580, 2012). "Pretreatment of macrophages with DPI or NAC did not reduce IL-1β release or cell death following KIM5 infection of macrophages for 8 or 24 hr." (PMID 22563435, 2012). "In addition, infection of murine macrophages with Y. pestis KIM results in YopJ-dependent activation of caspase-1 and secretion of high levels of IL-1β." (PMID 22563435, 2012). "WNV also induces a dramatic increase in several pro-inflammatory cytokines such as tumor necrosis factor alpha (TNF-α) and interleukin (IL)-1β and -6 and chemokines such as MCP-1 and IP-10, which regulate leukocyte trafficking into the brain, and neuronal death after infection." (PMID 22953001, 2012). "In the supplement to that manuscript, the authors reported that infection of THP-1 cells with VSV did not induce IL-1β production, although detailed methods for that study were not provided." (PMID 23056330, 2012). "Results indicate that absence of Vpr decreased MDM infection over time and that reduced the expression of selective proinflammatory cytokines IL-1β, IL-8 and TNF-α in MDMs at the transcript and/or protein levels." (PMID 22727020, 2012). "The reduced level for IL-6, IL-1β, TNF-α, and IFN-γ in lung may be a reason for the enhanced morbidity in VK627 and rTsE627K infections." (PMID 22719870, 2012). "It was not practical to test RIG-I deficient mice for IL-1β induction, because RIG-I deficient mice do not produce IFN in response to VSV and therefore rapidly succumb to infection." (PMID 23056330, 2012). "During infection in the CNS, JEV initiates a potent inflammatory response including microglial activation which subsequently results in the production of several pro- and anti-inflammatory cytokines including IL-1β and IL-18." (PMID 22393394, 2012). "The results from a single locus analysis in IL1B gene were reflected also in a haplotype level: The IL1B −511/ +3962 TC haplotype tended to be more frequent in PJI patients by comparison to those without infection after TJA." (PMID 22568934, 2012). "NLRC4 regulates Caspase-1 activation and IL-1β processing in response to infection with various gram-negative bacteria." (PMID 22701621, 2012). "Since RSV activates TLR signaling (via TLR2 and TLR4) during infection, we next investigated whether TLR/MyD88 pathway is required for IL-1β secretion during RSV infection." (PMID 22295065, 2012). "Acute CVB3 infection leads to a robust inflammation in cardiac tissue of wildtype mice, which is demonstrated by high numbers of infiltrated inflammatory cells and highly increased expression of proinflammatory cytokines such as IL-1β, IL-6, and TNF-α 10 days after infection." (PMID 22675647, 2012). "IL1β, IL6, IL12 and TNFα act proinflammatory and are known to be secreted by activated microglia in many different conditions, such as neurodegenerative disease, trauma or infection." (PMID 22647544, 2012). "In the brains infected with Pigeon04, mRNA expression levels of Mx1, OAS, IL6, IL1β and CCL5 were at least 17 fold higher than those of respective genes in the infected lungs on day 5 post infection when this virus almost similarly replicated in the lungs and brains." (PMID 21826229, 2011). "Surprisingly, Asc-/- mice, which should be equivalent to DKO because of the absence of IL-1β or IL-18, survived the infection." (PMID 22241982, 2011). "Macrophages infected with Yp-YopJKIM in thepresence of 30 mM NaCl appeared to secrete IL-1β to slightly lower levels ascompared to untreated infected macrophages at 8 hr post-infection, but thisdifference was not significant." (PMID 21533069, 2011).
infection (continued). "In the present study, there was a rapid shift from a Th1 immune response characterised by the expression of IFNγ and IL-1β genes to a regulated Th2 immune response characterised by the expression of IL-13, IL-10, TGFβ, and FOXP3 genes by seven days post infection (dpi) in the carrier lambs." (PMID 21385411, 2011). "A high MOI followed by 1 hrof bacterial-host cell contact before addition of gentamicin results in detectableYopJ-dependent apoptosis and caspase-1 activation within 2 hr of infection but nodetectable secretion of IL-1β by this time point (data not shown)." (PMID 21533069, 2011). "Interestingly, CTC administration only decreased expression of IL-17A mRNA at the late stage of infection in the current study, perhaps due to the concomitant down-regulation of TNF-α and IL-1β mRNA expression." (PMID 21943280, 2011). "At a number of different multiplicities of infection (MOI) the strain lacking pilin (PA103 ΔUΔT pilA-) failed to produce IL-1β secretion." (PMID 20955240, 2011). "In addition, infection with the H1N1 virus produced a decreased expression of the innate immune genes tested, including Mx, IL-1β and IL-6 than observed with the H5N9 virus." (PMID 21939525, 2011). "However, 30% of the mice treated with both the IL-1β and the TNF-α depleting antibodies succumbed to CO92ΔyopH infection." (PMID 20565713, 2010). "Strikingly, innate immune genes (whose transcript abundances are typically altered in response to other pathogens or insults including IL-8, CCL4, and IL-1β) showed no or very little change at any time point following infection." (PMID 22331987, 2010). "Our experiments had revealed that 16 hours after infection, the epidermis in resistant C57BL/6 mice is a major and stronger source not only for chemokines, but also for cytokines known to have the potential to induce Th1 cells (IL-12, IL-1β, TNFα and opn)." (PMID 20442861, 2010). "The absence of CPS results in increased induction of IL-1β, IL-6 and IL-8 in human gingival fibroblasts upon in vitro infection with viable P. gingivalis cells." (PMID 20064245, 2010). "The sensitivity of these mice suggests that IL-1β signaling activity is required for Nlrp1bS-mediated resistance and that macrophage sensitivity to LT is not the determining factor in infection outcome." (PMID 21170303, 2010). "While IL-18 expression did not change at any time point (data not shown), a robust up-regulation was detected in the expressions of IL-1β, -6, -8, and TNF-α at days 2 and 3 after infection with both MOI-1 and -5 of WNV, which coincided with increase in cell toxicity following WNV infection." (PMID 21034511, 2010). "At 16 weeks post-infection, Pycard−/− and Nlrp3−/− animals produced comparable if not enhanced levels of cleaved IL-1β compared to wild type mice." (PMID 20808838, 2010). "IL-1β was released by L. pneumophila in the presence or absence of caspase-7 after 24 hours of infection." (PMID 19343209, 2009). "In addition, in that study the intensity and level of expression of the genes analyzed (IL-8, GRO-α, GRO-β, TNF-α, IL-1β, TGF-β1 and IL-10) varied according to the step of infection (3, 10 and 24 h after the addition of bacteria to the cell culture)." (PMID 21637453, 2009). "In conclusion, we have shown that various TLR agonists and infection with Salmonella can induce IL-23, IL-18 and IL-1β, but not IL-12, production in monocytes and Mφ1." (PMID 20027291, 2009). "The levels of TNF-α, IL-1β and IL-6 in BAL before infection were similar in both groups." (PMID 19835595, 2009). "Upon administration of IL-1β polyclonal antibodies, the decrease in clinical scores, inflammatory responses, and protein levels of MIP-2 and KC was apparent at 1 and 3 days after infection (p<0.01)." (PMID 19590756, 2009). "Compared to TNF and IL-1β, the secretion of IL-6 and MCP-1 by THP-1 cells infected with vMyxM013-KO virus was first detected much later, and these were only measurable after 12 hours post infection." (PMID 19851467, 2009).
infection (continued). "At day 2 after infection significantly higher levels were evident only with regard to TNF-α production, but at the other time points assessed differences became statistically significant also for IL-6 and IL-1β production." (PMID 19606256, 2009). "Thus, local and systemic levels of IL-6, IL1β, TNF-α, MIP-1α, and MIP-2 were compared between IL-4−/− and control mice at 2, 5, and 10 days after infection." (PMID 19606256, 2009). "Furthermore, infection of THP-1 cells with vMyxM013-KO virus induced the activation of caspase-1 and processing and secretion of pro-inflammatory cytokines IL-1β and IL-18." (PMID 19851467, 2009). "Within the testis, the levels of expression of the immunosuppressive cytokines IL-10 and TGFβ and pro-inflammatory cytokines IFNγ, IL-1β, TNFα transcripts was not significantly changed following infection." (PMID 18347738, 2008). "However, BALB/c splenocytes produced higher proinflammatory cytokines such as IL-1β, TNF-α, IL-6, IL-18 than C57BL/6 splenocytes after infection with B. pseudomallei." (PMID 16919160, 2006). "In order to rule out the possibility that E/P-selectin mutant mice have enhanced basal levels of IL-1β due to low-grade infections, we measured basal IL-1β levels in nonimmunized E/P-selectin mutant mice kept on antibiotics for 2 weeks." (PMID 16207337, 2005). "In order to rule out the possibility that the elevated serum IL-1β levels in E/P-selectin mice were due to infections, we kept nonimmunized E-/P-selectin mutant mice on antibiotics for 2 weeks and then examined serum IL-1β levels." (PMID 16207337, 2005). "This shows that the elevated IL-1β in the serum of E/P-selectin mutant mice is not due to infection." (PMID 16207337, 2005). "Interestingly, a much higher level of interleukin (IL)-1β was secreted from NUF251-infected RAW264.7 cells as compared to those of NUF194-infected or LPS-treated cells, especially at 3 h post-infection, even though similar levels of IL-1β mRNA were detected in all these cells." (PMID 42012263, 2026). "Infection with strains harboring the S203P + G231N, E232T, N235D + N291D + A515V + S528G resulted in elevated PPAD activity, which correlated with clinical indicators of disease severity, induced COX-2 (~6-fold) and IL-1b (~7-fold) expression in osteoblasts and led to 94% reduction in OPG." (PMID 42205486, 2026). "Despite inducing robust secretion of proinflammatory mediators such as IL-6, IL-8, and TNF, RSV infection does not elicit a marked increase in IL-1β levels in bronchoalveolar lavage fluid, nasopharyngeal secretions, or systemic circulation during the early phase of infection." (PMID 41576161, 2026). "In addition, in the serum of infected chickens, higher levels of IL-1β compared to mock group were detected from 1 dpi to 7 dpi, and higher levels of TNF-α compared to mock group were detected from 6 hour post-infection (hpi) to 7 dpi." (PMID 40067802, 2025). "Similarly, expression of GBP1, NLRP3, and IL1B was downregulated in both HIF1‐KD and GBP1‐KD macrophages, while expression of ASC1 and HIF1A was upregulated in HIF1‐KD and GBP1‐KD macrophages, respectively, upon H37Rv infection, compared with controls." (PMID 41287823, 2025). "Macrophages migrate to the infection site via chemotaxis, where they recognize and phagocytize fungal pathogens while producing various pro-inflammatory cytokines and chemokines, including TNFα, CXCL1, CXCL2, CCL2, and IL-1β, thereby promoting inflammation and immune defense." (PMID 41190069, 2025). "Infection with MHV-68 resulted in an elevated abundance of cytokines (TNF-α and IL-6) that triggered inflammation, an upsurge in pyroptosis-related molecules involving caspase-1, IL-1β, and IL-18, along with a decrease in IL-10 concentration, an anti-inflammatory cytokine, in peritoneal macrophages." (PMID 40041420, 2025).
infection (continued). "The NLRP3 and IL-1β genes, which are involved in pyroptosis, a type of cell death mediated by inflammasome activation, were significantly upregulated in J774A.1 cells following infections with all strains compared to non-infected controls (p < 0.05)." (PMID 40727705, 2025). "Notably, aged animals did not exhibit elevated IL-1β levels in the lungs following SARS-CoV-2 P21 infection compared to their younger counterparts." (PMID 40016339, 2025). "Furthermore, IL-1β enhances the expression of adhesion molecules, including intercellular adhesion molecule-1 (ICAM-1) and vascular cell adhesion molecule-1 (VCAM-1), which facilitate immune cell recruitment to the site of infection or injury." (PMID 40155968, 2025). "LC patients showed slightly increased secretion of IL-1β, IL-6, TNF-α, GM-CSF and G-CSF, raising the possibility that other pro-inflammatory cytokines may also be disturbed, as observed by others 8 months after infection." (PMID 40566632, 2025). "Especially in the case of the proinflammatory cytosine TNF-α, there seems to be a close correlation with infections with atypical pathogens and a marked immune response, as well as with increased IL-1β and IL-6 values compared with the absence of infection (both in the presence and absence of PCOS)." (PMID 40647668, 2025). "Additionally, G-CSF, GM-CSF, MCP-1, FTL3L, IL-1β, and IL-12p70 cytokines were also not significantly induced by infection with the capsular serotype V strain, GB37, in gestational membranes or in the organ-on-a-chip models." (PMID 41277827, 2025). "Likewise, JBNU-22-N01 infection showed significantly increased levels of lung IFN-α, IFN-γ, IL-1β, and IL-12p40 at 7 dpi, indicating a faster disease progression and host response than PJ73 or VR2332, which is likely to be correlated with faster virus replication." (PMID 40459260, 2025). "Furthermore, IL-1β and IL-6 are major proinflammatory cytokines released by diverse immune and nonimmune cells upon stimulation, such as infection, injury, and stress." (PMID 39949769, 2025). "pullorum infection significantly elevated (p < 0.05) the renal (CREA, UREA), hepatic (ALT, AST), immunological (IgG, IgM), and inflammatory (TNF-α, IL-6, SAA, CRP) parameters, as well as the expression of trefoil factor 3, Toll-like receptor 2, TNF-α, IL-1β, and IL-6." (PMID 41597538, 2025). "We first performed Ad‐Zmiz1 infection with or without IL‐1β treatment in chondrocytes." (PMID 40040621, 2025). "Similarly, we observed that IL-1β levels do not increase after plateauing 24 hours after establishing the coculture, suggesting that secondary infection does not further amplify inflammasome activation." (PMID 39229127, 2025). "Furthermore, an increased concentration of the pro-inflammatory cytokine TNF-α was found in the lungs of TRαKO mice at the peak of infection, whereas other cytokines, e.g. IL-1β and IL-6, were not altered." (PMID 41159501, 2025). "BR15 infection induced a modest but statistically significant increase in TNF-α expression (p < 0.05) and a significantly higher expression of IFN-β1, IL-1β, IL-6, and IL-10, as well as the chemokines CCL2 (MCP-1), CCL5 (RANTES), and CXCL8 (IL-8), compared to MR766-infected cells." (PMID 40732762, 2025). "However, in this study there were no detectable differences in IL-1β plasma levels as a result of MA10 infection." (PMID 41497643, 2025). "It is unclear whether PwCF have increased IL-1β production in the absence of infection due to an intrinsic increase in NF-κB activity or because of the loss of CFTR function." (PMID 40791588, 2025). "However, although IL-1β transcripts were induced by d7 post-infection, IL-1β treatment of fibroblasts did not reproduce the strong inhibition of HCMV spread we observed in MyD88-expressing cells." (PMID 40638072, 2025). "Interestingly, infection with the strain lacking both ybjX and virK genes further enhanced the release of IL-1β, supporting once again a role for YbjX." (PMID 41144768, 2025).
infection (continued). "However, infection failed to elicit the release of mature IL-1β, and this is consistent with our prior reports in murine osteoblasts." (PMID 40056352, 2025). "Importantly, they found that mice lacking IL-1β, as well as mice infected with an hMPV strain missing the small hydrophobic (SH) protein, whose infection led to reduced caspase-1 activation in vitro, had less severe disease compared to WT mice." (PMID 41011440, 2025). "Importantly, the frequency of Tem was associated with elevated levels of inflammatory cytokines in the sera (primarily interleukin (IL)-1β and IL-6), suggesting a potential link between the process of inflammation and the fate of CD4 T cells in 17ZR101 infection." (PMID 40096073, 2025). "Artepillin C is primarily known for modulating pro-inflammatory markers such as IL1β and, probably in the absence of acute infection or stressful conditions, upregulation of some markers, such as IL-1β, may occur." (PMID 40001954, 2025). "To determine whether IL-1β stimulation of CFT073 affects host immune responses, we evaluated the expression of selected C. elegans immune and stress-related genes following CFT073 infection." (PMID 41162597, 2025). "To test this hypothesis, we determined levels of IL-1β release during infection with M. tuberculosis of macrophages containing or lacking NLRP11." (PMID 40272180, 2025). "Here, we used both in vivo chicken infection models and in vitro primary renal epithelial cell cultures and found that IBV activates the NLRP3 (NOD-like receptor family, pyrin domain containing 3) inflammasome, leading to the maturation and secretion of IL-1β (interleukin-1 beta)." (PMID 41334910, 2025). "Interestingly, in severe influenza A virus (IAV) infection, GSDMD promotes disease in mice, but infection-induced release of IL-1β is also independent of GSDMD." (PMID 40016339, 2025). "Upon A-431 cells infection with G. vaginalis, the levels of IL-8, IL-1α, and IL-1β did not change, irrespective of the pretreatment or not with BL, even though a trend of increased IL-8 could be observed in BL-primed as compared to un-primed infected cells." (PMID 40384982, 2025). "Unlike the ‘cell-free’ infection conditions in which we previously observed an increase in IL-1β levels 4 hours post-infection, we did not detect measurable differences in IL-1β secretion at this early timepoint following the establishment of SUPT1:MDM coculture." (PMID 40522834, 2025). "We found that both parent H1N1 and H1N1-E158A viruses induced cardiac IFNβ, TNF, IL-6, IL-18, and IL-1β above levels seen in mock control animals and that the H1N1-E158A virus induced higher levels of each inflammatory cytokine than the parent virus at day 5 post infection." (PMID 40909698, 2025). "In the innate immune system, AMs serve as the earliest replicative ecological niche for Mtb, and upon infection by Mtb, ESAT-6 secretion system 1 (ESX-1) induces inflammasome activation and, subsequently, the formation of caspase-1 can cleave gasdermin-D (GSDMD) pores and the release of IL-1β." (PMID 39456188, 2024). "The mRNA levels of IL-1β, IL-6, and CCL20, which are known to trigger an inflammatory response, peaked at 6 h following infection with M. gallisepticum in HD-11 cells and tracheal epithelial cells, then gradually decreased and reached the baseline 24 h post-infection." (PMID 38474071, 2024). "This study showed that B5 could not kill K. pneumoniae in vitro; however, intranasal B5 promoted the recruitment of macrophages and dendritic cells in the lungs in the early infection phase, and inhibited the secretion of TNF-α, IL-1β, and IL-17 in the lungs in the later infection phase." (PMID 39408834, 2024). "This suggests that, following effective control of the initial infection, IL-1β levels do not continue to rise, nor does ferroptosis further increase, which indicate that ferroptosis in the early stage of infection is consistently balanced in relation to the level of bacterial infection." (PMID 39353913, 2024).